CD36 (CD36 molecule (CD36 blood group))
Diseases named in the same sentence as CD36 in open-access papers (continued):
Sharing a sentence is not in itself a finding about the gene and the disease.
lung adenocarcinoma (5 papers, 2023 to 2025). A carcinoma that arises from the lung and is characterized by the presence of malignant glandular epithelial cells. "Moreover, palmitic acid or high‐fat diet promoted interaction between CD36 and Src kinase leading to its activation, which finally resulted in actin network remodelling in lung adenocarcinoma cells." (PMID 40418213, 2025). "Thus, CD36 shRNA or chemical inhibitor SSO directly inhibited the lung adenocarcinoma cell proliferation and actin remodeling-involved metastasis." (PMID 37612265, 2023). "Whether and how CD36 facilitates lung adenocarcinoma (LUAD) growth in high-fat environment is unknown." (PMID 37612265, 2023). "The copy numbers of both the target (CYP2C8, CYP3A4) and the reference genes (ALB, B2M, BCKDHA, F5, CD36, MPO, TBP, RPPH1) established in primary lung adenocarcinoma by the qPCR-based method were congruent with those determined by next-generation sequencing (for 10 genes, slope = 0.9498, r2 = 0.72)." (PMID 37686184, 2023).
multiple sclerosis (5 papers, 2022 to 2023). A progressive autoimmune disorder affecting the central nervous system resulting in demyelination. "In multiple sclerosis, which is mainly characterized by neuroinflammation, microglia can recognize and phagocytose extracellular myelin debris through the fatty acid translocase CD36." (PMID 36529923, 2023).
ovarian tumors (5 papers, 2018 to 2024). "CD36 is highly expressed in metastatic ovarian tumors, reprogramming tumor metabolism to maintain rapid tumor growth and metastasis." (PMID 38319449, 2024). "The future study will examine the relationship between PTGIS and lipid metabolism molecules such as PPAR, FABP4, FASN, and CD36, as well as the effect of fatty acid metabolism on the growth and invasion of ovarian tumorous cells." (PMID 36785673, 2023). "Former research investigated that the increased expression of CD36 promotes tumor metastasis, and mediates a pro-apoptotic effect in ovarian tumor cells." (PMID 31074374, 2019). "A recent study showed upregulation of CD36 in metastatic versus primary human ovarian tumours; moreover, blocking CD36 with monoclonal antibodies resulted in reduced tumour burden in a mouse xenograft model." (PMID 30069479, 2018). "Indeed, the expression of CD36 increases in metastatic ovarian tumors compared to matched primary tumors." (PMID 34063116, 2021).
pancreatic ductal adenocarcinoma (5 papers, 2021 to 2025). An infiltrating adenocarcinoma that arises from the epithelial cells of the pancreas. "In pancreatic ductal adenocarcinoma, the αvβ3 integrin and CD36 mediated cell growth and adhesion by binding THBS2." (PMID 38339060, 2024). "Interestingly, many patients with pancreatic ductal adenocarcinoma (PDAC) are resistant to gemcitabine; CD36 affects gemcitabine resistance by regulating anti-apoptotic proteins, and high CD36 expression in PDAC is critical for poor prognosis." (PMID 38276607, 2024).
retinal degeneration (5 papers, 2009 to 2025). Degeneration of the retina. "Taken together our data demonstrates that Cd36 deficiency inhibits retinal inflammation and retinal degeneration in Cx3cr1 knockout mice." (PMID 31969887, 2019). "Rats carrying a specificgenetic variant of CD36 have been shown to be more susceptible tolight-induced retinal damage, and are more likely to develop anage-related retinal degeneration and choriocapillary rarefaction." (PMID 20157514, 2009). "Augmentation of autophagy‐associated phagocytic receptors such as CD36 may be another potential therapeutic intervention for retinal degeneration." (PMID 40956390, 2025). "In retina, previous studies reported the role of CD36 in mitigating the proinflammatory responses of the mononuclear phagocytes (MNPs) in Cx3cr1−/− and light-induced mouse models of retinal degeneration." (PMID 39187498, 2024). "Our findings suggested that the protective effect of microglia during retinal degeneration was dependent on Trem2 expression and carried out via the activation of PPARγ and the consequent upregulation of CD36 expression." (PMID 39187498, 2024). "Taken together, our study underscored the importance of TREM2 in regulating microglia activation, and identified PPARγ signaling and CD36 as potential mechanisms and effector molecules of TREM2 in the context of retinal degeneration." (PMID 39187498, 2024).
silicosis (5 papers, 2009 to 2025). Silicosis is a respiratory disease caused by breathing in (inhaling) silica dust. "The rat silicosis model was induced by intratracheal injection of 10 mg silica per rat and CD36 expression was silenced by administration of a lentiviral vector (Lv-shCD36)." (PMID 19439069, 2009). "The Fibr-2 macrophage subset likely represents end-stage profibrotic macrophages in the silicosis lung due to waning expression of profibrotic genes coupled with increased expression of foamy macrophage markers including Spp1, Cd36, and lipid-metabolizing genes such as Lgals3 and Lrp1." (PMID 38985878, 2024). "Accordingly, CD36 may participate in the activation process of L-TGF-β1 in the early phase of the experimental silicosis." (PMID 19439069, 2009). "Furthermore, silencing expression of CD36 prevented the development of silicosis via inhibiting the activation of L-TGF-β1." (PMID 19439069, 2009). "So, we presume that CD36 also repeatedly participates in the activation of L-TGF-β1 and the pathological process of silicosis." (PMID 19439069, 2009). "Importantly, we showed that blocking lipid uptake/signaling by either inhibiting CD36 or PPARγ was highly effective in reducing TGF-β to these combined exposures, suggesting targeting these molecules might be effective in the treatment of silicosis." (PMID 30674959, 2019).
amyloid (4 papers, 2016 to 2023). "Moreover, blocking of the Nogo/NgR pathway promoted expression of CD36 which might increase clearance of Aβ and further ameliorate amyloid load in APP/PS1 mice." (PMID 30029608, 2018). "SAA receptors, such as SELS (glucose homeostasis and ER stress), ABCA1, ABCA7, SCARB1 (cholesterol efflux), CD36, TLR2, TLR4, CST3 (inflammatory signaling), FPR2 (chemotaxis and immune cell activation), and AGER (amyloidosis), have been reported previously." (PMID 27799725, 2016). "Loss of CD36 was associated with suppression of ROS production in BAM and reduction of brain Aβ1–40, the Aβ species that predominates in vessels, but not Aβ1–42, which predominates in amyloid plaques." (PMID 37789345, 2023). "Loss of CD36 was associated with suppression of ROS production in BAM and reduction of brain Ab1 − 40, the Aβ species that accumulates in vessels, but not Ab1 − 42, which accumulates in amyloid plaques." (PMID 37162996, 2023). "When examining amyloid deposition, we found that parenchymal amyloid plaques were not reduced, but CAA was markedly attenuated both in pial and parenchymal microvessels in CD36−/− → Tg2676 compared to WT → Tg2676 chimeras." (PMID 37789345, 2023).
autoimmune disease (4 papers, 2021 to 2024). A disorder resulting from loss of function or tissue destruction of an organ or multiple organs, arising from humoral or cellular immune responses of the individual to their own tissue constituents. "While little is known about the role of ApoC-2 in autoimmune diseases, the role of its receptor CD36 is more established." (PMID 34556808, 2021). "Moreover, the differential expression of HLA family molecules, particularly in relation to MYD88 and CD36, aligns with previous findings on the role of HLA genes in immune response and autoimmune diseases." (PMID 38919626, 2024). "CD36 could uptake autoantigens, including apoptotic cells and oxidized LDL, thereby prompting inquiries into the potential involvement of CD36 in B cells in the pathogenesis of autoimmune diseases." (PMID 38762740, 2024). "The activation of PPARγ enhances Treg responses through up-regulating CD36/CPT1-mediated fatty acid oxidation and subsequent N-glycan branching of TβRII/IL-2Rα, which is beneficial for inflammatory and autoimmune diseases." (PMID 35392915, 2022).
bacteremia (4 papers, 2010 to 2025). "Compared to wild type (Cd36+/+) mice, CD36-deficient (Cd36-/-) mice are more susceptible to experimental S. aureus infection, exhibiting higher mortality, increased levels of bacteremia, and multiple renal and cardiac abscesses." (PMID 20950462, 2010). "The class B scavenger receptor CD36 has been reported to predominantly mediate S. aureus clearance by murine phagocytes, and CD36-deficient mice fail to efficiently remove S. aureus in vivo resulting in profound bacteremia and high mortality." (PMID 24058538, 2013). "As a result, CD36-knockout mice fail to efficiently clear S. aureusin vivo, resulting in profound bacteremia." (PMID 36802172, 2023).
chronic myeloid leukemia (4 papers, 2019 to 2025). "This idea has already been demonstrated in gonadal adipose tissue, which fuels FA oxidation in CD36+ leukemic stem cells (LSC) and protects them from chemotherapy in a mouse model of blast crisis chronic myeloid leukemia (CML)." (PMID 31109063, 2019). "Patients with chronic myelogenous leukemia (CML) and high expression of CD36 often have worse prognoses, higher levels of FAO in the leukemia stem cell subgroup of CML, and resistance to AraC, but the specific relationship between FAO and drug resistance and its mechanism is still unclear." (PMID 40514365, 2025).
clear cell renal cell carcinoma (4 papers, 2019 to 2026). "In renal cancer, most frequently clear cell renal carcinoma (ccRCC), which has a typical metabolic phenotype, CD36 is involved in lipid accumulation and oxidative stress pathways." (PMID 42164471, 2026). "CD36 is underpinned to be involved in adipose absorption, but its role in clear cell renal cell carcinoma (ccRCC) remains unclear." (PMID 31528216, 2019). "In this study, we investigated the immunohistochemical expression of CD36, FATP4, and ACSL1 in 180 cases of clear cell renal cell carcinoma (RCC) in comparison with 80 specimens of the normal kidney." (PMID 31089396, 2019).
dementia (4 papers, 2012 to 2022). Loss of intellectual abilities interfering with an individual's social and occupational functions. "The product of the CD36 gene is a glycoprotein involved in lipid metabolism and trafficking both of which are key mechanisms contributing to the neurodegeneration in AD24–26 thus making CD36 an eminent molecule of interest when searching for mechanisms of the dementia-related neuronal loss." (PMID 35768560, 2022). "While there are various possible interpretations of this observation, the most parsimonious conclusion would seem to be that the DAT-onset associated CD36 polymorphisms may offer a (limited) protection against the disease by significantly delaying the appearance of dementia symptoms." (PMID 35768560, 2022). "Better understanding of CD36 involvement in dementia-related mechanisms could lead to novel therapies." (PMID 35768560, 2022).
depression (4 papers, 2021 to 2024). "In a study in mice, Alloprevotella was found in higher abundance in individuals with lower chronic stress-induced depression-like behaviors due to the deactivation of the class B scavenger receptor CD36, which is involved in the cytotoxicity associated with inflammation." (PMID 39436904, 2024). "The CD36 deficiency in CD36−/− mice alleviated chronic stress-induced depression-like behaviors." (PMID 33414380, 2021). "Depression-like symptoms in mice subjected to unpredictable chronic mild stress were relieved after CD36 knockout, and analysis of gut microbiota in CD36 KO mice revealed a significant increase in the abundance of Alloprevotella." (PMID 37089558, 2023). "A systematic network study with several other brain regions would better elucidate the mechanism of CD36 in depression." (PMID 33414380, 2021). "The results of this study may imply that CD36 has a brain-specific role in depression and acts through the lipid and inflammation pathway of the hippocampus." (PMID 33414380, 2021). "We measured CD36 expression in depressed mice as well as in patients with depression." (PMID 33414380, 2021). "For this purpose, we used CD36−/− knockout mice to investigate whether CD36 participates to the induction of depression-like behaviors by regulating the inflammasome and the gut microbiome." (PMID 33414380, 2021). "We conducted approaches to investigate the critical role of CD36 in the development of depression." (PMID 33414380, 2021). "In this study, we investigated whether CD36 affects depression by modulating the microbiota-gut-inflammasome-brain axis." (PMID 33414380, 2021). "To examine the involvement of CD36 in depression, we used the CSDS mouse model of depression." (PMID 33414380, 2021). "Moreover, we examined the levels of CD36 in PBMCs of patients with depression." (PMID 33414380, 2021). "Although CD36 has been associated with the inflammasome, the role of CD36 in the gut microbiota-inflammasome-brain axis hypothesis of depression has not been studied to date." (PMID 33414380, 2021). "We used CD36−/− (knockout) mice subjected to chronic social defeat stress, and measured the expression of CD36 in these depressed mice and in patients with depression." (PMID 33414380, 2021). "Further, ASC mRNA and protein were altered in CD36−/− mice, indicating that ASC may be required for CD36-mediated regulation of NLRP3 activation and depression." (PMID 33414380, 2021). "Taken together, our results indicate that CD36 is critical for the development of depression-like behaviors, and that it may therefore be a potential novel therapeutic target for the treatment of depressive disorder." (PMID 33414380, 2021).
falciparum malaria (4 papers, 2008 to 2020). "Platelet activation markers (PAC1 and CD36) were observed to be significantly (p > 0.05) associated with increased risk of falciparum malaria." (PMID 32268918, 2020). "We have analysed the role of polymorphic variants of ICAM-1 in severe falciparum malaria using static and flow based adhesion assays and CD36 in static assays only." (PMID 21390226, 2011). "The results indicate the significance of specific genetic variants of ICAM1, PECAM1 and CD36 in influencing the outcome of falciparum malaria in Indian populations." (PMID 19055786, 2008). "The data highlights the significance of variations in the ICAM1, PECAM1 and CD36 genes in the manifestation of falciparum malaria in India." (PMID 19055786, 2008). "Mutations in the human genes ICAM-1, CD36 and globin genes have been associated with susceptibility to severe falciparum malaria, in some but not all populations." (PMID 21390226, 2011). "CD36 is not expressed on areas of brain endothelium where cytoadherence occurs and binding to ICAM-1 on brain endothelium is implicated in the pathophysiology of severe falciparum malaria with coma." (PMID 22305466, 2012).
Hepatitis (4 papers, 2020 to 2025). Inflammation of the liver. "The team further demonstrated that KC CD36 phagocytosed modified lipids (eg, oxidized low-density lipoprotein, oxLDL), resulting in cholesterol accumulation in lysosomes and causing liver inflammation, thereby elevating the risk of NASH." (PMID 39774047, 2025).
hypertrophic cardiomyopathy (4 papers, 2022 to 2025). A condition in which the myocardium is hypertrophied without an obvious cause. "CD36 deficiency is a common condition in patients with hypertrophic cardiomyopathy but has also been reported in rare cases of DCM." (PMID 36292100, 2022). "However, there is a lack of reports on the effects of CD36 on muscle components, especially on skeletal muscle cells, and only a few reports on CD36 deficiency in hypertrophic cardiomyopathy, yet the conclusions remain controversial." (PMID 36111143, 2022).
influenza infection (4 papers, 2012 to 2023). "The previous data using ConA implicated IFNβ in the influenza-induced decrease of CD36." (PMID 27701435, 2016). "In the present study, we have used a previously validated in vitro model of lung macrophages to further investigate the role of CD36 in the effects of influenza infection on macrophage phagocytic function." (PMID 27701435, 2016). "Our data demonstrating influenza and RSV induced decreases in CD36 expression are in line with a recent report of gene expression changes in alveolar macrophages in response to influenza infection." (PMID 27701435, 2016). "Macrophages are essential to maintaining lung homoeostasis and recent work has demonstrated that influenza-infected lung macrophages downregulate their expression of the scavenger receptor CD36." (PMID 27701435, 2016). "Influenza infection significantly decreased mRNA level of macrophage receptors CLEC7A, MSR1, CD36, and MRC1." (PMID 22396727, 2012). "However, the mechanisms by which influenza infection affects CD36 expression and function of human macrophages has not been fully elucidated." (PMID 27701435, 2016).
lupus nephritis (4 papers, 2019 to 2024). Glomerulonephritis in the context of systemic lupus erythematosus. "CD36 knockout podocytes with CRIPR/cas9 system were used to elucidate the underlying mechanisms of podocyte injury stimulated by IgG extracted from lupus nephritis patients compared with that extracted from healthy donors." (PMID 35999224, 2022). "In conclusion, our study demonstrated that CD36 promoted podocyte injury in lupus nephritis by activating the NLRP3 inflammasome and inhibiting autophagy." (PMID 35999224, 2022). "Based on previous findings, our results suggested that CD36 promotes podocyte injury by activating the NLRP3 inflammasome in lupus nephritis." (PMID 35999224, 2022). "In our present study, we observed that upon stimulation with IgG extracted from lupus nephritis patients, CD36 was upregulated in podocytes, and NLRP3 inflammasome levels and podocyte apoptosis were increased in vitro." (PMID 35999224, 2022). "We analyzed the expression level of CD36 in glomerular tissues under different severity of LN evaluated by WHO Lupus Nephritis Class." (PMID 31592160, 2019). "However, the molecular mechanisms by which CD36 functions in the pathogenesis of podocyte injury in lupus nephritis remain elusive." (PMID 35999224, 2022). "Our results indicated that upregulated CD36 promoted podocyte injury in lupus nephritis." (PMID 35999224, 2022). "Recent study revealed that CD36 might also take part in the lipid disorders in the glomerular tissue of lupus nephritis by weighted gene co-expression network analysis (WGCNA) of GSE104948 from the GEO database." (PMID 35999224, 2022). "Whether the aberrant expression of CD36 contributes to the lipotoxicity damage in lupus nephritis deserves further study." (PMID 35999224, 2022). "Moreover, we further demonstrated that the expression level of CD36 is related to the WHO Lupus Nephritis Class of LN patients with the help of Nephroseq database." (PMID 31592160, 2019). "However, whether CD36 promotes podocyte injury by regulating the NLRP3 inflammasome in lupus nephritis remains to be established." (PMID 35999224, 2022). "Furthermore, our findings revealed for the first time that CD36 was upregulated in podocytes from patients with lupus nephritis and might promote podocyte injury by activating the NLRP3 inflammasome." (PMID 35999224, 2022). "In vitro, CD36, NLRP3 inflammasome, and autophagy were elevated accompanied with increased podocyte injury stimulated by IgG extracted from lupus nephritis patients compared that from healthy donors." (PMID 35999224, 2022). "We observed that CD36 and NLRP3 (NLR family pyrin domain containing 3) were upregulated in the podocytes of lupus nephritis patients and MRL/lpr mice with renal impairment." (PMID 35999224, 2022).